TREM1 (triggering receptor expressed on myeloid cells 1)
Diseases named in the same sentence as TREM1 in open-access papers (continued):
Sharing a sentence is not in itself a finding about the gene and the disease.
subarachnoid hemorrhage (8 papers, 2020 to 2025). A serious neurological disorder characterized by intracranial hemorrhage into the subarachnoid space. "Consistent with our result, the level of TREM‐1 expression was increased in microglia and endothelial cells in subarachnoid hemorrhage rats." (PMID 37170484, 2023). "In a rat model of subarachnoid hemorrhage, triggering receptor expressed on myeloid cells 1 (TREM-1) further worsens neuroinflammatory injury by activating NLRP3 inflammasome-induced microglia pyroptosis." (PMID 35722622, 2022).
Crohn disease (7 papers, 2012 to 2025). A gastrointestinal disorder characterized by chronic inflammation involving all layers of the intestinal wall, noncaseating granulomas affecting the intestinal wall and regional lymph nodes, and transmural fibrosis. "In addition, another recent study demonstrated that TREM-1 expression was associated with the common IBDs, ulcerative colitis (UC), and Crohn's disease (CD)." (PMID 22611379, 2012). "The pretreatment TREM-1 expression levels of CD14+ monocytes of Crohn’s disease (CD) patients were predictive of outcome to anti-TNF mAb therapy, with low TREM-1 expression associated with response to anti-TNF." (PMID 33790898, 2021). "This study assessed whether baseline triggering receptor expressed on myeloid cells [TREM-1] whole blood gene expression predicts response to anti-tumour necrosis factor [anti-TNF] therapy in patients with ulcerative colitis [UC] or Crohn’s disease [CD]." (PMID 37801628, 2024).
endotoxemia (7 papers, 2014 to 2025). "Experimental data have demonstrated that the upregulation of neutrophil and monocyte membrane TREM-1 during endotoxemia is associated with an elevated release of sTREM-1 in the blood." (PMID 39649719, 2024). "Studies in humans have shown that upregulation of monocyte- and neutrophil-membrane TREM-1 during endotoxemia is associated with an increased release of sTREM-1 in blood and other biological fluids." (PMID 30616644, 2019). "MAb TREM-1 stimulates the expression of large amounts of TREM-1 during endotoxemia." (PMID 24959004, 2014).
Neonatal sepsis (7 papers, 2020 to 2025). Systemic inflammatory response to infection in newborn babies. "In recent years, with the novel discovery of the role of TREM-1 expression in neonatal sepsis, an update of its diagnostic values is extremely necessary to meet the demands of clinical work." (PMID 35935355, 2022). "A comprehensive search was performed to identify the diagnostic and prognostic predictive values of the TREM-1 expression level in neonatal sepsis." (PMID 35935355, 2022). "In addition, the mRNA transcription and protein expression level of TREM-1 on the cell surface were qualitatively analyzed in the diagnostic value of neonatal sepsis." (PMID 35935355, 2022). "The data related to the diagnostic accuracy of TREM-1 expression in neonatal sepsis." (PMID 35935355, 2022). "The purpose of this study is to investigate the role of TREM-1 as a biomarker in the diagnosis and prognosis of neonatal sepsis." (PMID 35935355, 2022). "In that case, we also qualitatively analyzed the role of TREM-1 mRNA and mTREM-1 in the diagnosis and/or prognosis of neonatal sepsis." (PMID 35935355, 2022). "The biggest advantage of this study is that it is the first to comprehensively explore the role of TREM-1 expression in the diagnosis and prognosis of neonatal sepsis." (PMID 35935355, 2022). "The purpose of this systematic review was to explore the value of the expression level of the triggering receptor expressed on myeloid cell-1 (TREM-1) in the diagnosis and prognosis of neonatal sepsis." (PMID 35935355, 2022). "The study showed that TREM-1 was a potential biomarker for the diagnosis and prognosis of neonatal sepsis." (PMID 35935355, 2022). "Characteristics of the included studies that explored the prognostic value of TREM-1 expression in neonatal sepsis." (PMID 35935355, 2022). "While, compared with the diagnosis of neonatal sepsis, TREM-1 mRNA had higher accuracy (AUC: 0.902 vs. 0.708) in predicting the mortality of neonatal sepsis." (PMID 35935355, 2022). "We determine the impact of the eCIRP/TREM-1 interaction on systemic inflammation, cardiac function, and survival in a mouse model of neonatal sepsis." (PMID 33276725, 2020). "Pharmacologic inhibition of the eCIRP/TREM-1 interaction is a new potential therapeutic strategy in the treatment of neonatal sepsis." (PMID 33276725, 2020). "Inhibition of eCIRP/TREM-1 interaction with M3 is cardioprotective, decreases inflammation, and improves survival in neonatal sepsis." (PMID 33276725, 2020). "We further demonstrate that M3, an eCIRP-derived TREM-1 inhibitor, decreases systemic, pulmonary, and cardiac inflammation, improves cardiac dysfunction, and increases survival in a murine model of neonatal sepsis." (PMID 33276725, 2020). "TREM-1 plays a crucial role in neonatal sepsis by amplifying the inflammatory response." (PMID 41226426, 2025). "Therefore, it was necessary to quantitatively and qualitatively analyze the value of TREM-1 expression in the diagnosis and prognosis of neonatal sepsis." (PMID 35935355, 2022). "Since one study did not involve the diagnostic value of TREM-1 expression in neonatal sepsis, we only evaluated the quality of the remaining 12 studies." (PMID 35935355, 2022). "However, there are some limitations in this study, such as the reduced number of clinical studies on TREM-1 expression as a biomarker of neonatal sepsis, regional bias, and differences in detection methods." (PMID 35935355, 2022). "With a comprehensive analysis, sTREM-1 was demonstrated to be a credible biomarker for the diagnosis and prognosis of neonatal sepsis; TREM-1 mRNA and mTREM-1 may be potential markers for the diagnosis and/or prognosis of neonatal sepsis." (PMID 35935355, 2022). "In addition, TREM-1, which has been proposed as an early biomarker of neonatal sepsis, is involved in the amplification of neutrophil and monocyte inflammatory responses by stimulating pro-inflammatory cytokines." (PMID 33659006, 2021).
Neonatal sepsis (continued). "Finally, we demonstrate the therapeutic potential of M3 as an inhibitor of eCIRP/TREM-1′s interaction in neonatal sepsis." (PMID 33276725, 2020). "Hence, the lower methylation levels observed in the promoters of genes involved in neutrophil activation (i.e., ATP8B4, LRG1, TREM1, PRTN3, S100A8, ELANE, and CD177) illustrates the role of DNAm in innate immunity in neonatal sepsis." (PMID 33659006, 2021).
osteoarthritis (7 papers, 2016 to 2022). A noninflammatory degenerative joint disease occurring chiefly in older persons, characterized by degeneration of the articular cartilage, hypertrophy of bone at the margins and changes in the synovial membrane. "While symptomatic osteoarthritis is associated with an elevated level of acute phase reactants in the blood the role of TREM-1, HMGB-1, and RAGE are yet to be defined in musculoskeletal pathology." (PMID 27792788, 2016). "TREM-1 was found to play a critical role in osteoarthritis development through the regulation of NF-κB signaling." (PMID 33390769, 2021). "In canonical pathway analysis, most inflammation-associated signal pathways were upregulated in noTC cultured BMDMs, at both basal level and after LPS stimulation, including HMGB1 signaling, osteoarthritis pathway, p38 MAPK signaling, IL8 signaling and TREM1 signaling." (PMID 35874686, 2022). "Because TREM-1, HMGB-1, and RAGE affect inflammation in pathologic musculoskeletal conditions such as osteoarthritis, pharmacological manipulation of these mediators may represent a novel therapeutic approach to treat a variety of debilitating diseases." (PMID 27792788, 2016).
Parkinson disease (7 papers, 2019 to 2025). A progressive degenerative disorder of the central nervous system characterized by loss of dopamine producing neurons in the substantia nigra and the presence of Lewy bodies in the substantia nigra and locus coeruleus. "Inhibition of TREM‐1 reduces the inflammatory response during acute gout attacks, alleviates the neuro‐inflammatory response of Parkinson's disease." (PMID 34750987, 2021).
systemic inflammatory response syndrome (7 papers, 2011 to 2023). SIRS is a serious condition related to systemic inflammation, organ dysfunction, and organ failure. "In our study cardiac TREM1, which is an amplifier of the systemic inflammatory response syndrome, continuously increased over time in WT mice after CASP surgery reaching the level of significance after 36 h." (PMID 23935245, 2013). "Cell-activating receptor TREM-1 (triggering receptor expressed on myeloid cells 1) regulates congenital immune response and contributes to systemic inflammatory response syndrome (SIRS) development." (PMID 24049646, 2012).
alcoholic liver diseases (6 papers, 2019 to 2022). A disorder caused by damage to the liver parenchyma due to alcohol consumption. "Blockage of TREM-1 expressed on neutrophils and monocytes/macrophages decreases the activation of neutrophils and monocytes/macrophages and mRNA expressions of inflammation-associated genes in alcoholic liver disease of mouse model." (PMID 31649630, 2019). "Our results and other recent reports have demonstrated that TREM-1 signaling contributes to proinflammatory pathway activation in liver injury, fibrosis, alcoholic liver disease, and NAFLD." (PMID 31616301, 2019). "We further demonstrated that these LPC can therapeutically inhibit TREM-1 in various inflammatory diseases, including CIA, pancreatic cancer, retinopathy of prematurity, and alcoholic liver disease." (PMID 36012120, 2022).
cognitive decline (6 papers, 2017 to 2025). "TREM2 mutations have been associated with several neurodegenerative diseases and TREM1 variants with cognitive decline and Alzheimer-related amyloid pathology." (PMID 28303091, 2017). "In addition, rs6910730G within the TREM1 gene was found to be associated with an increased burden of neuritic plaques, Aβ deposition and cognitive decline in AD patients." (PMID 36068612, 2022). "TREM-1 activation in microglia amplifies neuroinflammation, disrupts metabolism, and impairs mitochondrial function, contributing to cognitive decline." (PMID 41226426, 2025). "TREM1, which shares homology with TREM2, has also been linked to AD amyloid pathology and cognitive decline." (PMID 30746447, 2019). "Protein quantitative trait analysis of human monocytes revealed that the rs6910730G variant in the TREM1 locus was associated with a decreased TREM1/TREM2 ratio and increased pathological features of AD and aging-related cognitive decline." (PMID 31426806, 2019). "Thus, TREM-1 promotes cognitive decline in aging and AD, highlighting its role in disease pathogenesis and its therapeutic potential." (PMID 41226426, 2025).
ischemia (6 papers, 2019 to 2024). A hypoperfusion of the BLOOD through an organ or tissue caused by a PATHOLOGIC CONSTRICTION or obstruction of its BLOOD VESSELS, or an absence of BLOOD CIRCULATION. "In a mouse model in which ischemia was pharmacologically induced, it was observed that TREM-1 promotes the production of IL-1β, IL-18, IL-6, CXCL-2, MCP-1, and CXCL-1 in microglia." (PMID 39062850, 2024). "Consistently, we found that ischemia-induced TREM-1 promoted IL-1β, IL-18, IL-6, CXCL-2, MCP-1, and CXCL-1 productions in microglia as well as the expression of MPO and ICAM-1 following ischemic injury." (PMID 31324751, 2019). "Immunofluorescence staining showed that the number of TREM1-positive microglia was noticeably increased in the penumbra region after tMCAO compared with that in the sham group, indicating that ischemia/reperfusion brain injury triggered the upregulation of TREM1 expression in microglia." (PMID 38468280, 2024). "It appears that TREM1/3 KO TECs due to the metabolic meltdown cannot longer cycle and that the impaired metabolic flexibility leave them unable to cope with the sudden energy deprivation experienced during ischemia." (PMID 31354698, 2019). "However, the possibility exists that microglial TREM-1 may be interacted with other proteins in ischemia-induced cerebral immune responses." (PMID 31324751, 2019). "After pharmacologic inhibition of TREM-1 with synthetic peptide LP17, ischemia-induced infarction and neuronal injury were substantially alleviated." (PMID 31324751, 2019).
pancreatic cancer (6 papers, 2020 to 2025). "As in our previous studies in mice bearing other pancreatic cancer xenografts, ligand-independent TREM-1 blockade by using GF9 and GA31-LPC was well tolerable in this study (data not shown)." (PMID 41404075, 2025). "Preclinical study showed that blockade of TREM1 specifically suppresses key cytokines and thereby inhibited tumor growth in human pancreatic cancer xenografts and prolonged the survival of mice." (PMID 35002712, 2021). "Furthermore, it has been suggested that TREM-1 inhibition reduces pancreatic cancer (PC) tumor growth and extends survival in PC mouse models." (PMID 40917508, 2025). "In our study, we explore the potential of a ligand-based strategy to modulate myeloid cell activity within the pancreatic cancer TME, drawing parallels to the effects observed with TREM-1 activation but employing a different mechanism of action in another cancer type." (PMID 40917508, 2025).
pancreatitis (6 papers, 2012 to 2025). Inflammation of the pancreas. "In conclusion, our data suggest that TREM-1 participates in pancreatitis-associated IBD, and pretreatment with LP17 is able to reduce the severity of intestinal injury." (PMID 22611379, 2012). "TREM-1 pathway blockade by LP17 treatment may suppress pancreatitis-associated IBD and ameliorate the damage to the intestinal mucosa barrier." (PMID 22611379, 2012). "Thus, we investigated the effect of TREM-1 pathway modulation on a rat model of pancreatitis-associated IBD." (PMID 22611379, 2012). "Furthermore, TREM1 induces intestinal barrier dysfunction associated with pancreatitis." (PMID 33954188, 2021). "In our study using the rat model of induced SAP, both serum soluble TREM-1 levels and membrane-bound TREM-1 expression in intestine tissue were significantly increased at 6 h after the induction of pancreatitis, and those increased levels persisted over time." (PMID 22611379, 2012). "The TREM-1 enhanced inflammatory response was observed in noninfectious disease models, including hemorrhagic shock, pancreatitis (acute inflammation), chronic inflammatory bowel diseases, and inflammatory arthritis." (PMID 39418109, 2024).
autoimmune disease (5 papers, 2017 to 2024). A disorder resulting from loss of function or tissue destruction of an organ or multiple organs, arising from humoral or cellular immune responses of the individual to their own tissue constituents. "Other notable associations included multiple Th17 associated pathways, autoimmune diseases, and other pathways that have also previously been linked to treatment resistance including oncostatin M and TREM1 signaling." (PMID 36192482, 2022). "Promising data are collected by investigating the prognostic impact and immunological relevance of TREM-1 expression in autoimmune diseases to identify a new strategy to improve the efficacy of immunotherapy in autoimmune diseases and in cancers as well." (PMID 38541074, 2024). "Furthermore, an association between TREM-1 expression and disease activity has also been observed in non-infectious diseases such as autoimmune diseases." (PMID 37168858, 2023).
Cerebral ischemia (5 papers, 2021 to 2025). Restriction of arterial blood supply to the brain associated with insufficient oxygenation to support the metabolic requirements of the tissue. "TREM1 also impaired cerebral ischemia-induced neuronal injury by inhibiting pyroptosis by targeting LP17." (PMID 39187376, 2024).
Cognitive impairment (5 papers, 2020 to 2025). Abnormal cognition is characterized by deficits in thinking, reasoning, or remembering. "Also, TREM1 replacement by microglial overexpression as well as activation of TREM1 signaling reversed Aβ pathology and ameliorated cognitive deficits." (PMID 32973446, 2020). "Knocking out TREM1 in the brains of APP/PSEN1 mice has been shown to increase Aβ1–42 levels and total amyloid plaque burden, and selective overexpression or activation of TREM1 on microglia cells could improve Aβ neuropathology and rescue AD-related spatial cognitive impairments." (PMID 39626951, 2024). "TREM-1 knockout specifically in endothelial cells alleviated BBB dysfunction and cognitive impairments." (PMID 41451290, 2025).
colon carcinoma (5 papers, 2019 to 2025). "Specifically, these shared pathways with IBD were linked to inflammation (TNF, IL-1A, IL-1B, NFkB, IL-6) and growth (TREM1, TGFB1), while other pathways shared with colon cancer were associated with colorectal metastatic signaling, growth (TREM1, NFkB and HMGB1) and inflammation (IL-8, IL-6)." (PMID 35323693, 2022). "TREM1-expressing colon tumors feature an overexpression of innate pro-inflammatory genes associated with tumorigenesis, while TREM1-deficient tumors feature an increased expression of genes related to adaptive immunity." (PMID 31546668, 2019). "In lung and colon cancer, increased TREM1 promotes tumorigenesis." (PMID 35323693, 2022).
coronary artery disease (5 papers, 2016 to 2025). "TREM-1 contributes to the expansion and instability of atherosclerotic plaques, which can be seen clinically as either coronary artery disease (CAD) or angina when the coronary is partially blocked or atherosclerotic myocardial infarction (AMI) when it is fully blocked." (PMID 41226426, 2025). "Previous studies have reported that S100A12 was an important inflammatory marker in coronary heart disease, therefore, TLR4 and TREM1 were further studied." (PMID 34221733, 2021).
dengue (5 papers, 2016 to 2025). "We investigated circulating soluble TREM-1 (sTREM-1) levels in 244 children and young adults aged 1–26 years with dengue fever presenting to an outpatient clinic in the Philippines." (PMID 40455726, 2025). "TREM1 acts as an amplifier of the immune and inflammatory response in vivo, and modulation of TREM1 has been shown to impact a number of inflammatory conditions, including septic shock, and acute dengue virus infection." (PMID 26873097, 2016).